ALDH1A3 (aldehyde dehydrogenase 1 family member A3)
Diseases named in the same sentence as ALDH1A3 in open-access papers (continued):
Sharing a sentence is not in itself a finding about the gene and the disease.
cholangiocarcinoma (7 papers, 2018 to 2025). A carcinoma that arises from the intrahepatic biliary tree (intrahepatic cholangiocarcinoma) or from the junction, or adjacent to the junction, of the right and left hepatic ducts (hilar cholangiocarcinoma). "We demonstrated that the ALDH1A3 level was positively correlated with cholangiocarcinoma cell migration ability." (PMID 34440089, 2021). "In conclusion, by using the LINCS program, we discovered that a JAK2 inhibitor, ruxolitinib, can downregulate ALDH1A3 expression and inhibit cell proliferation and migration in cholangiocarcinoma cell lines." (PMID 34440089, 2021). "Cryptotanshinone inhibited ALDH1A3 expression and cell migration, as well as inhibiting cholangiocarcinoma cell growth synergistically with gemcitabine." (PMID 34440089, 2021). "In this study, we found a positive correlation between ALDH1A3 protein expression levels and the cell migration abilities of three cholangiocarcinoma cell lines, which was verified using ALDH1A3-overexpressing and ALDH1A3-knockdown clones." (PMID 34440089, 2021). "We also used ALDH1A3-high and ALDH1A3-low populations of cholangiocarcinoma cell lines from the library of integrated network-based cellular signatures (LINCS) program and assessed the effects of ruxolitinib, a commercially available JAK2 inhibitor." (PMID 34440089, 2021). "In this study, we chose a listed JAK2 inhibitor, ruxolitinib, which inhibits ALDH1A3 expression in vitro and cholangiocarcinoma cell migration." (PMID 34440089, 2021). "Collectively, these results showed that the anti-tumor effect of ruxolitinib on cholangiocarcinoma partially depends on ALDH1A3." (PMID 34440089, 2021). "ALDH1A3 levels were higher ALDH1high than ALDH1low cells, which is consistent with observations in human cholangiocarcinoma cells." (PMID 30559934, 2018). "High ALDH1A3 predicted lymph node metastasis in patients with cholangiocarcinoma." (PMID 41210994, 2025). "ALDH1A3 knockdown in cholangiocarcinoma bile duct cancer cell lines decreases migration." (PMID 36672441, 2023). "Because ALDH1A3 enhances the cell migration ability in cholangiocarcinoma cell lines, we performed the wound-healing assay to examine whether ruxolitinib, an ALDH1A3 inhibitor, inhibited migration." (PMID 34440089, 2021). "Collectively, our studies suggest that ruxolitinib might suppress the ALDH1A3 activation through the JAK2/STAT1/3 pathway in cholangiocarcinoma, and trials should be undertaken to evaluate its efficacy in clinical therapy." (PMID 34440089, 2021). "To further examine ALDH1A3 expression and cell migration abilities, we established an ALDH1A3-overexpressing KKU-M005 cell line and knocked down ALDH1A3 in the KKU-M213 cell line, which expressed the highest ALDH1A3 levels among the three cholangiocarcinoma cell lines." (PMID 34440089, 2021). "Because ALDH1A3 is highly correlated with cholangiocarcinoma cell metastatic ability and stemness, a drug that inhibits or reverses the effect of ALDH1A3 may be therapeutically advantageous." (PMID 34440089, 2021). "To explore how ruxolitinib, a JAK2 inhibitor, reduces ALDH1A3 expression in cholangiocarcinoma cells, we used a microarray to investigate the transcription factors that fluctuate the most when applying different ruxolitinib concentrations to a cholangiocarcinoma cell line." (PMID 34440089, 2021). "The cholangiocarcinoma cell lines expressed higher ALDH1A3 than the normal MMNK-1 cells." (PMID 34440089, 2021). "Among cholangiocarcinoma patient specimens, specimens with higher levels of phosphorylated STAT1 and STAT3 exhibited higher ALDH1A3 expression and vice versa." (PMID 34440089, 2021). "To investigate the endogenous levels of ALDH1A3 in normal cells and tumor cells, we evaluated the protein expression level of ALDH1A3 in MMNK1, which is an immortalized human normal bile duct cell line, and in several cholangiocarcinoma cell lines—KKU-M055, KKU-100, and KKU-M213." (PMID 34440089, 2021).
malignant pleural mesothelioma (7 papers, 2015 to 2023). A malignant neoplasm that arises from mesothelial cells in the pleura and shows a diffuse growth pattern. "Recently, it has been reported that high ALDH1A3 expression is prognostic of poor survival in patients with malignant pleural mesothelioma (MPM), an asbestos-associated chemoresistant cancer." (PMID 37047661, 2023). "Chemoresistance is a hallmark of malignant pleural mesothelioma (MPM) management and the expression of ALDH1A3 is responsible for the survival and activity of MPM chemoresistant cell subpopulations (ALDHbright cells)." (PMID 34769499, 2021). "The regulation of ALDH1A3 gene has been investigated in the chemoresistant subpopulation of malignant pleural mesothelioma cells, which express ALDH1A3 as the main ALDH isozyme responsible for ALDH activity in these cells." (PMID 30733805, 2019). "Similarly, ALDH1A3 expression is a determinant in malignant pleural mesothelioma cell resistance to chemotherapy and in liver cancer, suggesting that it could be a new therapeutic target." (PMID 30622340, 2019). "In this work, by exploiting Malignant Pleural Mesothelioma as an experimental model of tumor chemoresistance, we demonstrated that a specific ALDH isoform, namely ALDH1A3, is enriched in chemoresistant mesothelioma cell subpopulations purified from multiple sources." (PMID 25868979, 2015). "Similarly, in malignant pleural mesothelioma, the STAT3- nuclear factor-kappa B/DNA Damage Inducible Transcript 3/enhancer-binding protein beta (STAT3-NF-kB/DDIT3/CEBPβ) axis was demonstrated to regulate ALDH1A3 expression and reduce sensitivity to pemetrexed + cisplatin treatment." (PMID 36672441, 2023).
coloboma (6 papers, 2009 to 2023). An abnormality in which a part of a structure in one or both eyes is missing. "In mouse, for instance, homozygous Aldh1a3 mutant embryos fail to complete the formation of the ventral cup of the eye and the closure of the chorioid fissure, resembling aberrations observed in colobomas in human retinas of patients with cat eye syndrome." (PMID 19478994, 2009). "Among these were the known human MAC genes TENM3, SMOC1, PAX2, ALDH1A3, and BMPR1B, in addition to NID1, VAX1, and NTN1, which have been previously identified as MAC or coloboma candidates based on animal studies." (PMID 36830662, 2023). "Aldh1a3-/- (Raldh3) knockout mice display coloboma, and although Aldh1a1-/- (Raldh1) knockout mice did not have a recognizable ophthalmic phenotype, double knockout Aldh1a1-/-; Alldh1a3-/- mice displayed an even more severe eye phenotype." (PMID 25004007, 2014).
liver cancer (6 papers, 2015 to 2025). An epithelial or non-epithelial malignant neoplasm that arises from the liver. "Data revealed that ALDH1A3 was broadly expressed and that MBE1.5 potently inhibited Aldefluor activity across most solid cancer types except liver cancer." (PMID 41210994, 2025).
neuroblastoma (6 papers, 2018 to 2024). Neuroblastoma (NB) is the most common solid, extracranial childhood tumor. "Analysis of the gene expression dataset from the TARGET study revealed that high expression of both ALDH1A2 and ALDH1A3 was associated with a worst outcome for neuroblastoma patients (n= 33/135 and 72/135 for ALDH1A2 and ALDH1A3 respectively)." (PMID 32483461, 2020). "In neuroblastoma cell lines expressing high levels of ALDH1A3, ALDH1A3 knockout via CRISPR/Cas9 gene editing results in decreased clonogenicity of tumor-initiating cells." (PMID 30733805, 2019). "In neuroblastoma cell lines expressing high ALDH1A3 levels, ALDH1A3 knockout via CRISPR/Cas9 gene editing reduced clonogenicity and mediated cell type-dependent inhibition of self-renewal properties of tumor inducing cells." (PMID 30087899, 2018). "Our findings support a potential interplay between MYCN and c-MYC upon glutamine deprivation, and we initially sought to investigate the co-expression of CSC-related genes such as ALDH1A1 and ALDH1A3 with MYC member expression in the paediatric neuroblastoma patient data from the TARGET study." (PMID 32483461, 2020). "We next focused our analyses on the expression of ALDH genes related to neuroblastoma CSCs, including ALDH1A2 and ALDH1A3." (PMID 32483461, 2020). "Our data revealed that ALDH1A1 and ALDH1A3 mRNA expression positively correlates with c-MYC gene expression in the neuroblastoma patient samples, and siRNA-mediated c-MYC knockdown inhibited expression of ALDH1A2 and ALDH1A3 genes in the MYCN-amplified neuroblastoma cells." (PMID 32483461, 2020). "Moreover, our results demonstrated an up-regulation of ALDH1A3 and downregulation of CD44 proteins upon glutamine starvation in MYCN-amplified neuroblastoma cells, while a downregulation of both CSC markers was observed in SH-SY5Y cells." (PMID 32483461, 2020). "Several studies have demonstrated that neuroblastoma contains a cell population having stem-cell like properties with enhanced expression of CSC markers including CD117, CD133, OCT4 and ALDH activity attributed to the expression of ALDH1A2 and ALDH1A3 proteins 13-16." (PMID 32483461, 2020).
Obesity (5 papers, 2017 to 2023). Accumulation of substantial excess body fat. "Specific inhibitors have been sought for ALDH1A1, ALDH1A1, and ALDH1A3 for treatment of Parkinson’s disease, obesity, cataracts, and various types of cancer." (PMID 35796328, 2023). "Aldh1a3 is not elevated in the islets from WD-fed mice or any of the lean control mice (not shown), which supports our interpretation that db/db mice display phenotypes consistent with human T2D while WD-fed C57BL/6 mice may represent an earlier, nondiabetic stage of obesity and insulin resistance." (PMID 29038790, 2017).
type 2 diabetes (5 papers, 2017 to 2025). "We have validated ALDH1a3 as an essential driver of pancreatic β cell loss whose inhibition restores insulin secretion in late-stage type 2 diabetes." (PMID 39133222, 2024). "In this study, conditional knockout of ALDH1a3 in β cells reverses dedifferentiation in models of type 2 diabetes, and treatment with a specific ALDH1a3 inhibitor causes the pancreatic islets to functionally regenerate, which is dependent on the loss of retinoid signaling." (PMID 39133222, 2024). "In type 2 diabetes and vascular proliferation diseases, ALDH1a3 has become a standard marker of cellular dedifferentiation, particularly in failing pancreatic β cells of both patients and mouse models." (PMID 39133222, 2024). "miR-483 was described as a protective factor in type 2 diabetes by repressing ALDH1a3 and knockout of miR-483 led to β cell dedifferentiation." (PMID 39133222, 2024). "Furthermore, there is a significant increase (>3-fold) in ALDH1A3 expression in the islets of subjects with type 2 diabetes as compared to healthy individuals." (PMID 39762647, 2025). "Dysregulated ALDH1A3 also has effects on other pathologies, including type 2 diabetes." (PMID 36672441, 2023). "Additionally, ALDH1A3 plays critical roles in other diseases, such as in the development of type 2 diabetes, where dysregulation of ALDH1A3 in pancreas β-cells impairs insulin production." (PMID 36672441, 2023).
intrahepatic cholangiocarcinoma (4 papers, 2018 to 2024). A carcinoma that arises from the intrahepatic bile duct epithelium in any site of the intrahepatic biliary tree. "In intrahepatic cholangiocarcinoma (bile duct cancer) ALDH1A3 was found to be the main contributor to Aldefluor activity." (PMID 36672441, 2023). "ALDH1A3 is an independent poor prognostic factor in patients with intrahepatic cholangiocarcinoma who underwent hepatectomy and those who received chemotherapy." (PMID 34440089, 2021).
lymph node metastasis (4 papers, 2020 to 2025). "On the other hand, lower expression of the CSC-associated genes ALDH1A3, LGALS3 and MYH9 and the pluripotency gene POU5F1 assessed by fingerprint values, were instead associated with the presence of lymph node metastases (LN Met)." (PMID 38124067, 2023). "Transcriptomic profiling revealed a molecular signature (ALDH1A3, CTXN1, MGAT3, and TMEM163) of occult lateral lymph node metastasis, exhibiting strong robustness (AUC = 0.857)." (PMID 40977710, 2025). "High ALDH1A3 also showed a significant association with a history of no tobacco use and was associated with the ADC histological type, early-stage tumors and tumors without lymph node metastasis." (PMID 32015486, 2020).
mesothelioma (4 papers, 2015 to 2024). A usually malignant and aggressive neoplasm of the mesothelium which is often associated with exposure to asbestos. "All of this will increase our confidence in ALDH1A3 as a marker and a key enzyme targeting some of the most aggressive and still hopeless cancers like GBM and mesothelioma." (PMID 39001459, 2024).
metastatic disease (4 papers, 2017 to 2024). "Altogether, these findings demonstrate an opposite association of ALDH1A1 and ALDH1A3 expression with PCa clinical outcomes and their differential expression in metastatic tumors." (PMID 38169509, 2024). "In patient tumours, ALDH1A3 and tPA are co‐expressed and their combined expression correlated with the TNBC subtype, high tumour grade and recurrent metastatic disease." (PMID 37753740, 2024).
ovarian tumors (4 papers, 2012 to 2025). "The available literature supports that ALDH1A3, ALDH3A2, and ALDH7A1 isozymes are expressed more abundantly in ovarian tumors, particularly in mucinous and endometrioid type tumors." (PMID 30965686, 2019). "Immunohistochemical staining showed significant overexpression of ALDH1A3, ALDH3A2, and ALDH7A1 isozymes in ovarian tumors relative to normal ovarian tissues." (PMID 22852552, 2012).
pulmonary arterial hypertension (4 papers, 2023 to 2025). Pulmonary arterial hypertension (PAH) is a group of diseases characterized by mean pulmonary artery pressure >20 mmHg and elevated pulmonary arterial resistance leading to right heart failure. "ALDH1a3 has also been implicated in a driving role in neointimal hyperplasia and pulmonary arterial hypertension (PAH) where it is induced in both human tissues and mouse models." (PMID 39133222, 2024). "A recent study reports ALDH1A3 is the most highly upregulated metabolic gene in pulmonary arterial hypertension." (PMID 36672441, 2023). "In addition, ALDH1A3 promotes H3K27ac in pulmonary arterial hypertension by converting acetaldehyde to acetate." (PMID 38669046, 2024). "Mice lacking ALDH1A3 are resistant to developing pulmonary arterial hypertension and ALDH1A3 regulates mRNA expression of cell cycle and metabolic genes involved in pulmonary arterial hypertension that is necessary for ALDH1A3-dependent proliferation and glycolysis." (PMID 36672441, 2023).
sarcoma (4 papers, 2013 to 2026). A usually aggressive malignant neoplasm of the soft tissue or bone. "Both ALDH1A3 abundance levels and activity were significantly upregulated in early-phase (immortalized) and fully transformed (sarcoma forming) cells as compared to normal MSCs." (PMID 41514266, 2026). "Altogether, these results show that SOX2, ALDH1A1 and ALDH1A3 expression, together with their associated ALDEFLUOR activities are progressively enhanced in CSC subpopulations during sarcoma progression toward more aggressive phenotypes." (PMID 27292183, 2016). "This indicates that sarcoma cell lines are useful for molecular and epigenetic studies, especially for hypermethylated genes (for example, ALDH1A3) but are only of limited use for hypomethylated genes." (PMID 24345474, 2013). "A strong negative correlation was observed between DNA methylation status and expression of ALDH1A3 for the whole sarcoma collection." (PMID 24345474, 2013). "ALDH1A3 had the highest negative correlation between DNA methylation and gene expression in the whole sarcoma collection and was downregulated in MLS samples compared to normal fat." (PMID 24345474, 2013).
autism (3 papers, 2015 to 2023). Persistent deficits in social interaction and communication and interaction as well as a markedly restricted repertoire of activity and interest as well as repetitive patterns of behavior. "Individuals with biallelic ALDH1A3 variants have been previously reported with additional variable systemic features, including severe neurodevelopmental delay and autism, in addition to bilateral A/M." (PMID 36997679, 2023). "Though no clear evidence supports a link between variants in ALDH1A3 with autism, mouse studies show that lack of Aldh1a3 (Gene NC_000073.6) results in abnormal GABAergic neuronal differentiation in the forebrain basal ganglia." (PMID 26352270, 2015).
Insulin resistance (3 papers, 2017 to 2021). Increased resistance towards insulin, that is, diminished effectiveness of insulin in reducing blood glucose levels. "A high level of ALDH1A3 is linked to β-cell dysfunction in NIDDM, but this gene may be responsible for the advancement of insulin resistance." (PMID 30678306, 2019).
thyroid cancer (3 papers, 2016 to 2022). "Our results showed that the transcriptional levels of ALDH1A1 and ALDH1B1 significantly decreased in thyroid cancer tissues, whereas that of ALDH1A3 increased." (PMID 35280765, 2022). "Here, we showed that ALDH1A1/B1 expressions were significantly decreased in thyroid cancer patients, but ALDH1A3 was elevated." (PMID 35280765, 2022). "As an example, ALDH1A3 was reported to be involved in the resistance of K1 thyroid cancer cells to a FAK inhibitor (Y15)." (PMID 26973599, 2016). "However, the role of ALDH1A3 in thyroid cancer development still needs further study." (PMID 35280765, 2022). "Moreover, high mRNA expression of ALDH1A3 only enhanced OS in male patients with thyroid cancer." (PMID 35280765, 2022). "Furthermore, immunohistochemical results verified that ALDH1A1, ALDH1A3, and ALDH1B1 were highly expressed in thyroid cancer at the protein level, suggesting the role of ALDH1A1/A3/B1 in thyroid cancer development." (PMID 35280765, 2022).
adenoma (2 papers, 2015 to 2025). A neoplasm arising from the epithelium. "Time series analysis using the likelihood ratios showed differences in expression of genes including Fos, Lama3, Aldh1a3, Col7a1 and Doks associated with increased induction by t = 12 h, whereas E2f8, Exo1, Clspn, Kif14 and Kif12 all were decreased in Smad4+/+ adenomas." (PMID 40348815, 2025). "In addition, ALDH1A3, COL1A2, FADS1, SFRP2, SULF1, and THBS2 were found to be significantly (p < 0.01) differentially expressed in tumour samples but not in adenomas compared to healthy samples." (PMID 26482433, 2015).
asthma (2 papers, 2021 to 2023). "Gene expression analysis indicated elevated ALDH1A3 expression in asthma patients; however, another study showed no change in ALDH1A3 protein expression levels." (PMID 36672441, 2023). "Additionally, ALDH1A3 and SMOX were also essential for childhood asthma and were enriched in the “beta-alanine metabolism” pathway." (PMID 34456632, 2021).
autism spectrum disorder (2 papers, 2015 to 2021). A spectrum of developmental disorders that includes autism, and Asperger syndrome. "Several missense mutations in ALDH1A3 have been identified in family studies of autosomal recessive microphthalmia, autism spectrum disorder, and other neurological disorders." (PMID 33474529, 2021). "This could be a possible explanation of a connection between ALDH1A3 mutations and the neurological symptoms displayed in patients with intellectual disabilities and autism spectrum disorder." (PMID 33474529, 2021).
benign prostatic hyperplasia (2 papers, 2021 to 2023). A non-cancerous nodular enlargement of the prostate gland. "In PCa cells, ALDH1A3 is higher in primary PCa with luminal phenotype than in benign prostatic hyperplasia (BPH) tissues and normal tissues." (PMID 36694633, 2023). "The authors have demonstrated that 6-substituted-imidazo[1,2-a] pyridine derivatives inhibited ALDH1A1 and ALDH1A3 gene expression and the proliferation of cancer cell line PC3, normal prostate epithelial cell line PNT2-C2, and benign prostatic hyperplasia cell line BPH1." (PMID 34572930, 2021).